FOXK2 (forkhead box K2)
Diseases named in the same sentence as FOXK2 in open-access papers (continued):
Sharing a sentence is not in itself a finding about the gene and the disease.
tumor (continued). "Finally, the in vivo functions of FOXK2 in tumor initiation and development still needs further in-depth studies using tissue-specific mouse models." (PMID 38741782, 2024). "Addressing these challenges will advance our understanding of FOXK2’s role in tumor formation, proliferation, invasion and metastasis, as well as in cancer therapy or drug resistance, eventually paving the way for targeting FOXK2 in the treatment of cancer and metabolic diseases." (PMID 38741782, 2024). "Additionally, SIRT1 catalyzes FOXK2 deacetylation, reducing tumor cell apoptosis and decreasing sensitivity to the chemotherapy drug cisplatin." (PMID 38741782, 2024). "The tumors formed by circFOXK2-deficient HCC cells exhibited a significantly smaller volume and lower tumor weight than the NC group, which could be restored by further treatment with a FOXK2-142aa overexpression plasmid." (PMID 36922872, 2023). "The effect of FOXK2 on tumor progression remains controversial." (PMID 36922872, 2023). "In addition, we transfected the FOXK2-142aa overexpression vector and si-LDHA into HCC cells and found that the exogenous knockdown of LDHA expression significantly weakened the pro-tumor effects of FOXK2-142aa." (PMID 36922872, 2023). "Additionally, FOXK2 participates in the regulation of a series of biological behaviors, such as tumor metabolism, autophagy, proliferation, invasion, and metastasis, via multiple signal pathways." (PMID 36172141, 2022). "FOXK2‐K223R mutation did not affect tumour cell growth in the absence of cisplatin treatment compared with that in mice inoculated with FOXK2‐WT cells." (PMID 34866322, 2022). "FOXK2 inhibits tumor proliferation, migration, and invasion and EMT process." (PMID 36172141, 2022). "A series of tumor-metabolism related genes are regulated by FOXK2 at the transcriptional level." (PMID 36172141, 2022). "Given that autophagy is an important cell biological behavior affecting tumorigenesis and tumor proliferation, we tested whether FOXK2 is involved in the regulation of autophagy levels in PTC cells." (PMID 35154454, 2022). "Furthermore, tumours in the shFOXK2‐ovWT group were smaller and weighed less than those in the FOXK2‐K223R group following cisplatin treatment." (PMID 34866322, 2022). "Despite its role as a tumor suppressor, some reports have attributed an oncogenic role to FOXK2." (PMID 36172141, 2022). "Limited previous studies indicated that FOXK2 could act either as an oncogene or as a tumor suppressor, depending on context." (PMID 35349489, 2022). "FoxK2 may be involved in developing liver cancer, and affect the initiation of tumor promoters by inhibiting cell proliferation and migration." (PMID 35903069, 2022). "The value of FOXK2 as a biomarker is likely highly tumor-specific, and even then may only apply to specific sub-types of specific tumors or to particular therapeutic regimes." (PMID 36172141, 2022). "These contradictory findings indicate that whether FOXK2 plays an oncogene or a tumor suppressor in tumor progression is tumor-specific." (PMID 35154454, 2022). "The function of FOXK2 is context and tumor-specific, and it might serve as an oncogene and tumor suppressor in different cancers." (PMID 33785763, 2021). "In human tumors, FOXK2 has been reported to act as either oncogene or tumor suppressor." (PMID 33313412, 2020). "FOXK2 has been reported to act as either oncogene or tumor suppressor." (PMID 33313412, 2020). "It is therefore currently unclear whether FOXK2 functions as a tumour suppressor or oncogene in this cancer type." (PMID 30897782, 2019). "Notably, FOXK2-depleted triple negative MDA-MB-231 cells injected in immunodeficient mice formed tumours exhibiting distant metastasis and increased growth rates, further confirming the data in the in vivo scenario." (PMID 30897782, 2019).
tumor (continued). "Moreover, nuclear FOXK2 expression was also significantly correlated with oestrogen receptor status and tumour stage." (PMID 26344694, 2015). "Based on our prior findings from immune infiltration analysis, a plausible explanation for this phenomenon could be attributed to alterations in tumor microenvironment components (e.g., CAFs), influencing the expression microenvironment of FOXK2 across distinct tumor types." (PMID 39552461, 2024). "Additionally, tumor tissue FOXK2 gene expression levels were assessed." (PMID 40212695, 2024). "In addition, tumors with up‐regulated FOXK2 expression often have lower tumor purity, which may be due to an increase in CAFs in the tumor microenvironment." (PMID 39552461, 2024). "However, no direct association between FOXK2 and the tumor microenvironment or immune response has been reported thus far; further investigation is warranted." (PMID 38741782, 2024). "The first report on the role of FOXK2 in cellular transformation came from the finding that interaction of the C-terminal region of the viral E1A protein with FOXK2 is required for adenoviral-mediated suppression of tumour formation in both in vitro and in vivo assays." (PMID 30897782, 2019). "Subsequently, we considered widely accepted tumor immunotherapy predictive indicators such as staging, age, IPS score, TIDE score, and TMB, and here we added FOXK2 expression levels." (PMID 39552461, 2024). "In future research, it is necessary to further investigate the functions of FOXK2 and FBXO32 in cancer cells and the tumor environment." (PMID 39552461, 2024). "By targeting FOXK2, an oncogene that activates the PI3K/AKT signaling pathway, miR-1271-5p inhibits tumor progression." (PMID 36927770, 2023). "In that study, XBP1s was shown to contribute to tumor progression by activating HIF-1α, a target we also found to be upregulated by FOXK2, downstream of IRE1α." (PMID 35349489, 2022). "FoxK2 is significantly elevated in HCC cells and correlates to tumor size, TNM stage, and tumor vascular infiltration." (PMID 35903069, 2022). "Not only the tumour-suppressive role of E1A, but also of E6 proteins from human papillomaviruses 21/14, is likely to depend on concomitant targeting of FOXK1 and FOXK2 via a conserved Thr-Ser-containing motif." (PMID 30897782, 2019). "Additionally, during the proliferation of tumor cells, we observed a significant increase in the OCR after 15 min of MP treatment following the knockout of FOXK2 compared to the sh-FOXK2 group." (PMID 40641601, 2025). "In the absence of cisplatin stimulation, FOXK2 remains hypoacetylated in the cell nucleus, impeding mitotic catastrophe and diminishing tumor cell apoptosis." (PMID 38741782, 2024). "Unlike other FOX family TFs, the functions of FOXK2 in cancer are less well understood, although its context-dependent and tumor-specific functions have been recently reported." (PMID 35349489, 2022). "FOXK2 might be involved in HCC carcinogenesis and function as a tumor promoter through suppression of cell proliferation and migration." (PMID 33313412, 2020). "FOXK2 has been reported to act as either oncogene or tumor suppressor; however, the effect of FOXK2 on the EMT has not yet been demonstrated in HCC cells." (PMID 33313412, 2020). "To verify the in vitro results, we established xenograft tumor models by subcutaneous injection of HCC cells transfected with an empty vector, an shRNA lentiviral plasmid targeting circFOXK2 (sh-circFOXK2), and sh-circFOXK2 + a FOXK2-142aa overexpression plasmid." (PMID 36922872, 2023).
cancer (24 papers, 2015 to 2025). A tumor composed of atypical neoplastic, often pleomorphic cells that invade other tissues. "In the context of BRCA, elevated levels of FOXK2 correlate with increased numbers of cancer‐associated fibroblasts (CAFs) and heightened infiltration of CD4 + TH2 cells, thereby indicating a poorer prognosis." (PMID 39552461, 2024). "This highlights the importance of FOXK2 as not only a diagnostic marker but also a potential therapeutic target in cancer management." (PMID 38741782, 2024). "The FOXK2 transcription factor has been implicated in cancer drug resistance, where it has been shown to modulate sensitivity to paclitaxel and epirubicin via inducing the expression of FOXO39." (PMID 29540677, 2018). "Recent evidence has linked FOXK2 to cancer cell proliferation and survival, but hitherto, a role in cancer chemotherapeutic drug resistance has not been established." (PMID 26344694, 2015). "Moreover, it underscores the need for further research to unravel the intricate molecular mechanisms underlying FOXK2’s function in cancer, ultimately leading to more effective treatments and improved patient outcomes." (PMID 38741782, 2024). "Dysregulation of FOXK2 has been linked to the development of cancers and other metabolic disorders." (PMID 38741782, 2024). "It is important to note that the molecular mechanisms contributing to FOXK2 gene deregulation are poorly understood for most cancers." (PMID 41959742, 2025). "CircFOXK2 (hsa_circ_0000816), one of the 50 most highly expressed circRNAs, drew our attention due to its parental gene, FOXK2, which exhibits diverse effects in various cancers." (PMID 40233410, 2025). "Hyperacetylated FOXK2 exhibits reduced nuclear distribution, significantly affecting cell cycle-related genes, leading to cell cycle arrest and promoting apoptosis of cancer cells." (PMID 38741782, 2024). "Overall, our pan‐cancer analysis showed that FOXK2 expression was negatively correlated with prognosis in some different cancer types during standard radiotherapy, chemotherapy, and immunotherapy." (PMID 39552461, 2024). "FOXK2 has the potential to be used as a prognostic indicator and target for treatment in individuals with cancer." (PMID 39552461, 2024). "We divided the TCGA dataset into high and low expression groups based on the median TPM expression of FOXK2 and screened 200 FOXK2‐related DEGs to investigate their potential functions in pan‐cancer patients." (PMID 39552461, 2024). "Melding metformin's action with FOXK2 silencing offers a tantalizing prospect, potentially unveiling a transformative paradigm in targeting the glycolytic trajectory for refined cancer therapy." (PMID 40212695, 2024). "Compared with the low group, the high FOXK2 expression group showed varying degrees of reduction in the infiltration of all immune cells except CD4 + Th2 cells and cancer associated fibroblasts (CAFs)." (PMID 39552461, 2024). "In most types of cancer, we found a correlation between increased FOXK2 expression and decreased immune score, indicating reduced immune cell infiltration." (PMID 39552461, 2024). "This research involved a thorough examination of the FOXK2 expression levels across 33 different types of cancer in the TCGA database, suggesting FOXK2 as a potential biomarker for predicting response to immunotherapy." (PMID 39552461, 2024). "In pan‐cancer, the high expression of FOXK2 indicates that patients have poor prognosis in terms of OS (p < 0.001) and disease‐free survival (DFS) (p < 0.001)." (PMID 39552461, 2024). "In all types of cancer with a significance level of p < 0.05, FOXK2 expression was negatively correlated with IPS score." (PMID 39552461, 2024). "The correlation between the expression level of FOXK2 and the chemoradiotherapy resistance and prognosis of locally advanced cancer patients after neoadjuvant chemotherapy has been validated." (PMID 39552461, 2024).
cancer (continued). "For instance, FOXO3 can also be deacetylated by SIRT1, and it collaborates with FOXK2 to regulate the apoptosis of cancer cells." (PMID 38741782, 2024). "The quanTIseq algorithm also calculated that in cancer, the T cell infiltration in the FOXK2 high expression group was significantly lower than that in the low expression group." (PMID 39552461, 2024). "Our research provides insights into the significance of FOXK2 in cancer and indicates its potential as both a prognostic indicator and target for treatment." (PMID 39552461, 2024). "As a potential downstream target gene for FOXK2, FBXO32 has been found to exhibit both cancer‐causing and anti‐cancer properties in different types of cancer." (PMID 39552461, 2024). "The analysis of integrated single‐cell data by cancer type revealed significant upregulation of FOXK2 in all cancer types compared to normal tissue." (PMID 39552461, 2024). "In cancer cells, the UPR pathway is usually activated, probably related to metabolic stress caused by accelerated nucleotide synthesis and cell proliferation, highlighting the role of FOXK2 metabolic regulation and protein homeostasis for cancer development." (PMID 38741782, 2024). "FOXK2 genes were analyzed using single‐cell sequencing in pan‐cancer bulk RNA‐seq from the TCGA database." (PMID 39552461, 2024). "Understanding these nuances is crucial for elucidating the precise role of FOXK2 in different cancer types and for developing targeted therapeutic strategies." (PMID 38741782, 2024). "Next, we matched the cancer types with significant differences in FOXK2 expression to normal organizations in the TCGA and GTEx databases." (PMID 39552461, 2024). "Nevertheless, there is a scarcity of comprehensive studies examining how FOXK2 affects the effectiveness of treatment across various types of cancer and alterations in the immune environment within tumors." (PMID 39552461, 2024). "Accumulating evidence indicates that the functions of FOXK2 are altered in cancers by PTMs, which affect the expression of FOXK2 target genes." (PMID 36172141, 2022). "Further, exploration of The Cancer Genome Atlas (TCGA) and Genotype-Tissue Expression (GTEx) databases revealed higher FOXK2 expression in human OC specimens (OV, n = 427) compared with normal FTE (n = 5)." (PMID 35349489, 2022). "Collectively, these results suggested that FOXK2 K223 acetylation levels obviously affected the expression of cell cycle–related and apoptosis‐related mRNAs in cancer cells following cisplatin stimulation." (PMID 34866322, 2022). "In conclusion, we have unveiled key functions of FOXK2 in the regulation of the UPR in cancer cells and CSCs." (PMID 35349489, 2022). "On the other hand, these target genes were upregulated in FOXK2-OE versus EV-transduced OC or non-cancer cells." (PMID 35349489, 2022). "Ultimately, the information presented here will help enhance the therapeutic potential of FOXK2 as a cancer target." (PMID 36172141, 2022). "In this study, SIRT1 inhibition enhanced FOXK2-induced chemosensitivity to cisplatin via acetylation at K223 of FOXK2, and FOXK2 K223 deacetylation reduced the chemosensitivity of cancer cells to cisplatin." (PMID 36172141, 2022). "Simultaneously, FOXK2 phosphorylation leads to chemo-resistance in cancer cells by modulating autophagy." (PMID 36172141, 2022). "We also demonstrated the molecular mechanisms through which FOXK2 deacetylation affected apoptosis in cancer cells treated with cisplatin." (PMID 34866322, 2022). "Consistent with previous studies, our results suggested that SIRT1‐mediated deacetylation of FOXK2 reduced apoptosis in cancer cells." (PMID 34866322, 2022). "Next, we further explored the effects of FOXK2 K223 acetylation on the chemosensitivity of cancer cells using stable transfection with shFOXK2‐ovNC, shFOXK2‐ovWT and shFOXK2‐ovK223R." (PMID 34866322, 2022).
cancer (continued). "Recently, an increasing number of studies have demonstrated that FOXK2 plays an important role in the transcriptional regulation of cancer." (PMID 36172141, 2022). "Studies have shown that the abnormal regulation of FOXK2 can suppress or promote the occurrence and development of certain cancers." (PMID 36172141, 2022). "Our data establish a previously unappreciated role of FOXK2 in regulating cancer stemness through fine-tuning the intracellular stress defense mechanism governed by IRE1α/XBP1." (PMID 35349489, 2022). "Particularly, we explore the emerging functions of FOXK2 as a regulator of a broad range of cancer features, such as cell proliferation and survival, DNA damage, metabolism, migration, invasion and metastasis." (PMID 30897782, 2019). "Conversely, FOXK2 depletion by siRNA increased cell viability and clonogenicity, and conferred resistance to these conventional cancer chemotherapeutic agents in MCF-7 cells." (PMID 26344694, 2015). "The expression, function, and involved pathways of FOXK2 in different types of cancer." (PMID 38741782, 2024). "FOXK2 may promote cancer cell proliferation by activating Wnt‐signaling through interaction with DVL (DVL is a stable activator of β‐catenin)." (PMID 39552461, 2024). "Next, we investigated the effect of PDK2 on cancer cell growth through phosphorylation of FOXK2 at Ser9, Thr13 or Ser30 and found that FOXK2 or Ser9-mediated induction of cancer cell proliferation could be induced by PDK2 overexpression in cells." (PMID 38734828, 2024). "FOXK2 plays a crucial role in the transcriptional regulation of various cancer types." (PMID 39020437, 2024). "Our objective in this research was to explore if FOXK2 could function as a prognostic indicator for the effectiveness of immunotherapy in different types of cancer." (PMID 39552461, 2024). "It has been reported that FOXK2 can yield heterogeneous effects in different types of cancer and may possess various biological functions." (PMID 36922872, 2023). "To investigate whether the PTM of FOXK2 affected chemosensitivity to cisplatin in cancer cells, we treated H1299 cells with the SIRT1 selective inhibitor EX527." (PMID 34866322, 2022). "FOXK2 is phosphorylated at Ser61 by checkpoint kinase 2 in the context of DNA damage; this traps FOXK2 in the cytoplasm, resulting in inhibition of apoptosis in cancer cells." (PMID 34866322, 2022). "Furthermore, increasing evidence has shown that FOXK2 itself and PTM of FOXK2 are associated with apoptosis in cancer cells." (PMID 34866322, 2022). "Additionally, we evaluated the prognostic value of FOXK2 expression in patients with various cancers." (PMID 36172141, 2022). "During the last few decades, some studies have reported FOXK2 expression in cancer patients." (PMID 36172141, 2022). "Functional roles of FOXK2 pathway in different types of cancer." (PMID 36172141, 2022). "Accordingly, hypoacetylated FOXK2 still localized in the nucleus and inhibited apoptosis in cancer cells, suggesting that FOXK2 K223 hypoacetylation may be involved in attenuation of chemosensitivity to cisplatin." (PMID 34866322, 2022). "Taken together, these findings suggested that FOXK2 and FOXO3 may be affected by opposing SIRT1‐associated molecular mechanisms under stress conditions, although the effects on cancer cell apoptosis were similar." (PMID 34866322, 2022). "Here, we introduce several important regulatory modes of FOXK2 in cancer." (PMID 36172141, 2022). "Here, we discuss the suppressive and promotive roles of FOXK2 in the context of cancer." (PMID 36172141, 2022). "Thus, in this review, we summarize the latest information regarding the molecular mechanisms by which FOXK2 expression and activity are regulated and the role of FOXK2 in cancer." (PMID 36172141, 2022). "Finally, we discuss the prognostic value of assessing FOXK2 expression in cancer patients and how it can be potentially targeted for future anticancer interventions." (PMID 30897782, 2019).